CD163 (CD163 molecule)
Diseases named in the same sentence as CD163 in open-access papers (continued):
Sharing a sentence is not in itself a finding about the gene and the disease.
tumor (continued). "PD-L1 expression in tumor cells can be used as a prognostic factor and is closely related to CD163+TAMs infiltration." (PMID 38970071, 2024). "Western blot results further demonstrated that the protein expression of M1 and M2 macrophage markers CD86 and CD163 in tumor tissues was significantly higher than in paracancerous tissues (p<0.05)." (PMID 39531417, 2024). "In the pre-treatment tissues, more stromal CD3 + FoxP3 + Tregs and CD86+/CD163 + macrophages were observed in patients with residual tumor existed in the resected lymph nodes (pN1), compared with patients with pCR." (PMID 38802821, 2024). "The mean numbers of CD68+ and CD163+ infiltrating macrophages in both the tumor nests and stroma were concordantly higher in LLT1-positive tumors compared to LLT1-negative tumors." (PMID 38673902, 2024). "Higher levels of pks+E. coli were associated with decreased serum CRP levels and reduced densities of CD4+ cells and CD163+ cells in the tumor-immune microenvironment." (PMID 39272861, 2024). "Higher levels of pks+ E. coli were associated with lower levels of the serum C-reactive protein, fewer densities of CD4+ cells and CD163+ cells in the tumor microenvironment, and a reduction in the number of organs affected by recurrent metastasis." (PMID 39272861, 2024). "K17 expression shields tumor cells from CD8+ T cells and recruits tumor promoting CD163+ M2 macrophages, indicating that K17 fundamentally impacts the immune response to PDAC." (PMID 38730319, 2024). "On the other hand, M2 macrophages, characterized by high expression of CD206, ARG1, and CD163, promote tumor progression by antagonizing anti-tumor T-cell immunity." (PMID 39719597, 2024). "Two populations were identified as tumor-associated macrophages (CD163+), with one having a more proinflammatory phenotype (TAM-Mac; tumor-associated macrophages) and moderate expression of TMEM119." (PMID 38758780, 2024). "The relationship between IDO1 and marker genes of tumor-associated macrophages (TAMs; CCL5, CD68, and IL10), M1 (IRF5, NOS2, and PTGS2), and M2 (CD163, VSIG4, and MS4A4A) macrophages was analyzed." (PMID 39351094, 2024). "We also found that OTUD4 OE in tumor cells enhanced a tumor-promoting M2-like phenotype in TAMs, usually defined by the expression of CD163." (PMID 38530357, 2024). "Surprisingly, CAFs induced significantly more differentiation to CD163+CD206+ TAMs than PDAC tumor cells (BxPC3)." (PMID 38594506, 2024). "The qPCR analysis (n = 66) revealed an elevated expression of RUNX1 in tumor tissues (P < 0.0001), and the positive associations between RUNX1 mRNA and CD163 mRNA, Arg1 mRNA, CD68 mRNA, CD206 mRNA, IL-10 mRNA were observed (all P < 0.05)." (PMID 38419056, 2024). "M2 macrophages (CD163+) have a pivotal mechanistic role in tumor growth, angiogenesis, and tumor invasion, primarily through their capacity to degrade the extracellular matrix." (PMID 38817895, 2024). "Since sCD163 levels go hand in hand with CD163 expression, we highlight below tumor types where such a role for CD163 or sCD163 has been explored or considered." (PMID 39451197, 2024). "The fluorescence expression of the M2 marker CD163 increased with the elevation of tumor stage, whereas the expression of the M1 marker CD86 was elevated in tumor tissues with lower tumor stages." (PMID 39531417, 2024). "Spatial heatmaps of SPP1 and CD163 confirm the localization of the expression of these genes in, respectively, the tumor and healthy regions of the tissue." (PMID 38217002, 2024). "Another study identified three TAM subtypes in the microenvironment of Granulomatous slack skin, exhibiting different functionalities where CD206(+)/CD163(+) showed an M2-like phenotype, potentially interacting with T cells to promote tumor progression." (PMID 39068459, 2024). "In a separate study, high CD163+ TAM infiltration was correlated with increased tumor aggressiveness and reduced progression-free survival." (PMID 39044824, 2024).
tumor (continued). "Comparing immune cell infiltration in the peritumoral area and tumor core of glioblastomas showed that CD163+ cells were more abundant in the tumor core, similarly to the higher expression of the immunosuppressive markers PD-L1, IDO, and TIGIT." (PMID 38542199, 2024). "Another study, which differentiated between macrophages in the stroma and the tumor parenchyma, found that CD163+ macrophage infiltration in the breast tumor stroma correlates with larger tumors, proliferation, and hormone receptor‐negative status." (PMID 38426622, 2024). "In primary tumor stage I, we subclustered 1161 DCs into seven distinct subclusters, identifying subcluster 1 as activated DCs (n = 211 cells), subcluster 2 as CD163+CD14+ DCs (n = 191 cells), and subcluster 4 as pDCs (n = 145 cells)." (PMID 38612588, 2024). "While CD163+ macrophages are usually regarded as immune-suppressing and tumor-promoting, human macrophages are likely to concurrently exhibit phenotypic characteristics of both M1-like and M2-like subtypes." (PMID 38720366, 2024). "One of the markers used to classify monocytes/macrophages as tumor-supportive is the scavenger receptor CD163." (PMID 39065651, 2024). "Genetic and pharmacological depletion of CD163+Tim4+ omental macrophages prevents tumor progression and the metastatic spread of disease." (PMID 39516356, 2024). "A study, which included a sample size of approximately 200 cases of pancreatic ductal carcinoma (PDC), revealed significant positive connections between tumor-infiltrating pan-macrophages, specifically CD163+ or CD204+ M2, and Neu." (PMID 38730579, 2024). "Results show increased expression of SLC1A5 and FAP by flow cytometry and confocal imaging, and CD163 (confocal imaging) in HCC827 tumor slices incubated with REVs or when co-cultured with HCC827-GR tumor slices." (PMID 39431017, 2024). "From staining with F4/80 and CD163 antibodies, more M1 macrophages infiltrating the tumor tissue were observed by administrating immune cells cultured on the CPSB ceramics than on the control and HAp surfaces." (PMID 39408898, 2024). "We analyzed CD11b+ tumor-infiltrating myeloid cells (TIMs), CD163+ tumor-infiltrating macrophages (TAMs), and CD8+ tumor-infiltrating lymphocytes (TILs) using immunohistochemistry and tissue microarrays." (PMID 39452540, 2024). "Pretreatment tumor tissue samples from a total of 44 patients were evaluated via immunohistochemistry for CSF-1 and CD163." (PMID 39734810, 2024). "Higher magnified view of tumor sections demonstrated that CD163+ macrophages were distributed in the perivascular niches in the tumor and at the brain interface." (PMID 39352749, 2024). "This study showed that elevated expression levels of CD47, CD68, and CD163 in tumor tissues are significantly correlated with poorer OS and PFS in patients with NPC." (PMID 39682556, 2024). "We found that CD163 expression was increased in the presence of VSCC (median 5 ± 0.2) compared with tumor-free lymph nodes (median 2 ± 0.5)." (PMID 38407373, 2024). "CD163 is thought to be extensively involved in angiogenesis, a role that can facilitate tumor re-growth and invasion." (PMID 39409905, 2024). "Emactuzumab (RG7155) is a mAb to CSF-1R that enhances T cell-mediated anti-tumor immune responses via a mechanism of specific inhibition of CSF-1R dimerization and consequent clearance of M2 macrophages expressing the CD163 antigen and CSF-1R." (PMID 39169402, 2024). "Numerous studies have demonstrated a significantly higher number of CD68+ macrophages and CD163+ M2-like phenotypes in the tumor mass and within infiltrative areas of glioblastoma patient post-bevacizumab therapy." (PMID 38787372, 2024). "Immunohistochemistry (IHC) analysis of the tumor tissues from mice in each group treated showed that the hypoxic sEVs-treated group had higher levels of CD163 expression in their tissues, suggesting a higher level of M2 macrophage infiltration." (PMID 38690261, 2024).
tumor (continued). "High stromal CD68+ and CD163+ TAM infiltration was associated with BC clinicopathological features, increased tumor recurrence and reduced overall survival (OS)." (PMID 39044824, 2024). "The immunophenotypic characterization verified the presence of a CD163+CD209+ double-positive TAM population from the tumor." (PMID 39498357, 2024). "Histologic sections were subjected to triple indirect sequential IF using WT1 to detect MM tumor cells, CD11c to identify M1 macrophages, and CD163 to identify M2 macrophages." (PMID 38592450, 2024). "Fluorescence immunostaining for the CAF marker αSMA and the M2 macrophage marker CD163 was performed for all resected tumors to quantify αSMA-positive areas and numbers of CD163-positive cells in the tumor area." (PMID 39000110, 2024). "Colorectal cancer: High CD163 expression at the tumor invasive front was correlated with high tumor grade, invasion, the presence of lymph node metastases, and low overall survival." (PMID 39451197, 2024). "The amount of tumor infiltrating M2 macrophages (CD163 +) also statistically significantly, but moderately/weakly, correlated with stiffness (r2 = 0.384, p = 0.018)." (PMID 38914647, 2024). "While the highest immune infiltrates were observed in the invasive margin for all immune cells, CD163+macrophages and Tregs had the highest tendency to infiltrate the tumor center." (PMID 39053947, 2024). "This was characterized by increased CD8+ cytotoxic T lymphocytes, CD20+ B lymphocytes, and tumor-suppressive (CD11c+) macrophages, along with a decrease in tumor-promoting (CD163+) macrophages." (PMID 38474224, 2024). "Macrophage populations were skewed towards elevated numbers of pro-inflammatory HLA-DR + /CD163- M1 type macrophages upon osimertinib treatment in the PC9 parental tumor cohort." (PMID 38702301, 2024). "Within the tumor center, especially B cells stayed at the tumor stroma, whereas CD163+macrophages, followed by T cells, were more often localized within tumor fields." (PMID 39053947, 2024). "On the contrary, factors secreted by the high-grade tumor cells have been shown to skew TAM differentiation into CD163 TAMs." (PMID 38893266, 2024). "Another limitation of our study is the lack of investigation of M1 functions in support of cancer stem cells and of evidence supporting the suggested ability of CD163/FKBP51s TAMs to migrate to brain areas far from the tumor." (PMID 38651817, 2024). "Specifically, TAM2 is a subtype of macrophages that promotes tumor progression and can be identified through various surface markers, including CD163, CD206, Fizz1, and Arg1." (PMID 38693304, 2024). "Within the same tissue area, CD163+ TAMs showed significant spatial correlations exclusively with CD68+ monocytes/macrophages (tumor: r = 0.42, P = 6 × 10−3; stroma: r = 0.43, P = 4 × 10−2; Pearson), confirming their subset classification as CD68+ cells." (PMID 38407373, 2024). "The proximity of CD163+CD206+M2 TAMs to tumor cells is closely related to the survival rate of patients." (PMID 38279145, 2024). "Consistent with their potential role in suppressing anti-tumour activities of T cells, CD163+ TAMs express a range of potent immunosuppressive molecules, including PD-L1, PD-L2, IL-10, and TGF-β." (PMID 38903497, 2024). "The numbers of both, CD68+ and CD163+ cells, were significantly increased in tumor-adjacent adipose tissue in overweight/obese patients." (PMID 39456610, 2024). "The most important markers of TAMs have been identified by studying tumours at different sites: CD163, CD204 (MSR1), CD206 (MRC1), MARCO, SIGLEC1 (CD169), stabilising protein-1 (Stab1) and Tie2 (TEK)." (PMID 39060648, 2024). "Macrophages are the most abundant immune cell type in the tumor microenvironment, and M2 type macrophages exhibit high levels of CD163 expression." (PMID 38627864, 2024). "Next, macrophages near the outside of the tumor tissue were observed from staining with F4/80 and CD163 antibodies." (PMID 39408898, 2024).
tumor (continued). "CD163 TAMs showed a strong correlation between their stromal and tumoral locations and infiltrated into the tumor nest." (PMID 38893266, 2024). "The angiogenic impact of the CD163+ macrophages on the vasculature of the tumor microenvironment leads to increased oxygenation and nutrition of the tumoral area, contributing to the final clinical outcome." (PMID 39451197, 2024). "RP tumour-infiltrating myeloid cells expressed high levels of molecules associated with immunosuppression (CD58, CD80, CD163), as well as monocyte activation and dendritic cell maturation (CD40)." (PMID 37758326, 2024). "Moving to primary tumor stage II, we subclustered 232 DCs into four subclusters, with subcluster 3 representing CD163+CD14+ DCs (n = 48 cells)." (PMID 38612588, 2024). "The Western blot results showed elevated CD163 expression in NB tumors at INSS stage IV compared to INSS I/II/III in 10 tumor tissues (n = 10)." (PMID 38714539, 2024). "We measured the levels of infiltration of CD163 + M2-TAMs in 92 ESCC tissues and found that increased infiltration of M2-TAMs in the tumor stroma was associated with a poor prognosis in patients as well as the expression levels of CD44 and OCT4." (PMID 36641471, 2023). "The expression of five markers (CD3/CD4/CD8/CD19/CD163) of tumor immune cells was evaluated retrospectively in tumor sections from 68 consecutive cases of TNBC by immunohistochemistry." (PMID 37090736, 2023). "For example, Tumor: CD163 purity (adjusted P-value = 0.0298), one of the adverse features in HER2+ cases, was not identified in machine learning." (PMID 36707660, 2023). "IHC staining results further confirmed that the expression of CD44 in tumor cells was positively associated with the number of CD68+ macrophages and CD163+ macrophages (P < 0.05)." (PMID 37316699, 2023). "IHC staining analysis revealed that CD163 was mainly expressed in tumor stromal regions in AEH/EEC tissues." (PMID 36373483, 2023). "Immunohistochemistry for CD68 (a pan-macrophage marker) and CD163 (a specific M2 macrophage marker, M2 macrophages are thought to facilitate tumor growth) was comparable between patients <40 years, 40–65 years, and >65 years." (PMID 37568649, 2023). "The expression level of SNHG17 was higher in TAMs compared to NTRMs, and SNHG17 had a strong degree of co-localization with CD163 in tumor tissues." (PMID 38098044, 2023). "In human breast tumors, CD68+ and CD163+ macrophages were significantly increased at the invasive front compared to the tumor core, and macrophages at the invasive tumor front positively correlated with tissue stiffness." (PMID 37296891, 2023). "In our study cohort, we observed statistically significantly more CD163+ M2-macrophages in the tumor margins than in the tumor center." (PMID 36836239, 2023). "Tumor-associated macrophages disproportionately show upregulation of SPP1 and downregulation of CD163, consistent with prior findings." (PMID 37426750, 2023). "CD163 is a hemoglobin scavenger receptor expressed in macrophages and is widely used as a marker for the M2-like/pro-tumor phenotype of TAMs." (PMID 36961655, 2023). "Specifically, the abundance of α-SMA+ CAFs correlated with CD163+ MØs, in addition, we observed significantly positive correlations among α-SMA+ CAFs, CD163+ MØs and anti-tumor immune cells (i.e. CTLA4, FOXP3, CD4 and CD8 T cells)." (PMID 37254126, 2023). "C. albicans infection caused the upregulation of CCL2 concentration as well as CD163, PD-L1, and GAL-9 expression on tumor-associated macrophages (TAMs) in oral tumors isolated from C3H/HeN-SCC VII mice." (PMID 37067414, 2023). "In this study, we collected CRC samples with different levels of differentiation, detected the infiltration of FoxP3+ Tregs, CD66b+ TANs, and CD163+ TAMs, and analyzed the relationship between cell infiltration and tumor cell differentiation." (PMID 37232465, 2023).
tumor (continued). "Some studies have explored the relationship between tumor cell differentiation and the infiltration of FoxP3+ Tregs, CD66b+ TANs, or CD163+ TAMs in the tumor microenvironment." (PMID 37232465, 2023). "CD8+ TILs demonstrate cytotoxicity toward tumor cells, while FoxP3+ TILs and CD163+ TAMs suppress antitumor immunity, contributing to tumor progression." (PMID 36764954, 2023). "In consistence with our previous findings, inhibition of CacyBP impaired tumor growth and decreased tumor infiltration of F4/80+CD163+ macrophages." (PMID 37968706, 2023). "This plot showed that M2-like macrophage markers (MRC1 and CD163) had lower scaled intensities at tumour cell proximity than other macrophage markers." (PMID 37002343, 2023). "We chose to analyze five immune markers (CD3+, CD4, CD8+, CD19+, and CD163) because they represent the main immune cell types (cytotoxic and regulatory T cells, B cells, and macrophages) and play key roles in tumor immunity." (PMID 37090736, 2023). "Tumor-associated macrophages (CD68, CD163), cytotoxic T cells (CD8), and regulatory T cells (FoxP3) were quantified via three methods." (PMID 37543970, 2023). "Moreover, higher CD163 expression may also be used to assess the activity of myeloid-derived suppressor cells (MDSCs), resulting in synergic protumoral activity and an increased risk of tumor recurrence." (PMID 37465638, 2023). "Results show that C3AR1 has the strongest correlation with M2 macrophages (CD163, MRC1, CD209), tumor-associated macrophages (CCL2, CD86, CD68) and monocyte immune markers, including (CD14, CD33, ITGAX)." (PMID 37005667, 2023). "M2-polarized macrophages that express CD163 promote angiogenesis and the production of matrix metalloproteinases, which enhances tumor growth and invasion." (PMID 36765852, 2023). "An unfavorable impact of CD163 expression on overall survival has also been observed for other tumor entities." (PMID 37876933, 2023). "In contrast, CD68+IRF8+, CD68+CD163+CD206+ macrophages were less enriched in both tumor and stroma regions." (PMID 37723144, 2023). "Pan-cancer analysis of the TCGA&GTEx database showed that CD206 and CD163 mRNA expression was heterogeneous among 33 malignant tumor tissues, but both were significantly highly expressed in PAAD tissues." (PMID 37662928, 2023). "Lactic acid produced by tumor cells as a by-product of glycolysis can lead to upregulation of the CD206 and CD163 genes in TAMs, which is linked to M2 polarization and immunosuppression." (PMID 38033495, 2023). "RFA-lip-GM-CSF increased CD163+ M2 macrophages in untreated index tumor compared to all groups (p<0.05), at 3d and 7d." (PMID 37883367, 2023). "It is possible that red pulp macrophages are positive for CD163 and CD206 expressed on M2-like macrophages and tumor-associated macrophages." (PMID 37553633, 2023). "The results show different densities of macrophage infiltration (M1/CD80 or M2/CD163) in both the tumor stroma (ST) and intratumoral (IT) areas." (PMID 37628994, 2023). "Different from other methods that solely relied on H&E WSIs to extract lymphocytes, the identifications of CD8, CD163, and PD-L1 provide extra information, which help us better characterize the tumor immune micro-environment." (PMID 36707660, 2023). "The released molecules by different cells in tumor stroma trigger infiltration of monocytes, CD11b+ and CD163+ TAMs into the OSCC tumor." (PMID 37221555, 2023). "In tumor specimens from CRC patients, higher A20 expression was closely associated with lower CD163 (+) macrophages infiltration." (PMID 37607946, 2023). "In patients with SD compared to those with PD, we found markers including CD163, EpCAM, PR, and B7-H3, enriched in the tumor compartment of patients with SD." (PMID 37153589, 2023).